PRRC2C (proline rich coiled-coil 2C)
Description:
Required for efficient formation of stress granules.
Synonyms: BAT2D1; BAT2L2; KIAA1096; XTP2; BAT2-iso
Tractability: PROTAC: UniProt records ubiquitination sites on it; ubiquitination databases record sites on it; its protein half-life has been measured.
Gene: Protein-coding gene on chromosome 1 (171,485,530 to 171,593,511, forward strand). Ensembl gene ENSG00000117523.
Subcellular location: Cytoplasm, Stress granule
Subcellular location (Human Protein Atlas): Cytosol
Gene Ontology:
Molecular function: protein binding; RNA binding
Biological process: stress granule assembly; hematopoietic progenitor cell differentiation
Cellular component: cytosol; membrane; cytoplasmic stress granule
Genetic constraint (gnomAD): Loss-of-function variants: 66 observed, 281.79 expected, observed/expected ratio (o/e) 0.23, 90% interval 0.19 to 0.29. The upper end of that interval is the gene's LOEUF score, 0.29, which puts it in group 1 of 6, group 1 being the genes least tolerant of losing a copy. Missense variants: 2,917 observed, 3,308.3 expected, observed/expected ratio (o/e) 0.88, 90% interval 0.85 to 0.91. Synonymous variants: 1,233 observed, 1,164.3 expected, observed/expected ratio (o/e) 1.06, 90% interval 1.01 to 1.11.
Homologues: Orthologues: macaque PRRC2C (98% identical), chimpanzee PRRC2C (97% identical), pig PRRC2C (90% identical), dog PRRC2C (87% identical), guinea pig PRRC2C (87% identical), rabbit PRRC2C (87% identical), rat Prrc2c (86% identical), mouse Prrc2c (86% identical), tropical clawed frog prrc2c (58% identical), zebrafish prrc2c (50% identical), Caenorhabditis elegans F52G3.1 (9% identical). Paralogues in human: PRRC2B (26% identical), PRRC2A (25% identical).
Diseases named in the same sentence as PRRC2C in open-access papers:
PRRC2C is named in the same sentence as 10 diseases in open-access papers, as found by Europe PMC text mining. Sharing a sentence is not in itself a finding about the gene and the disease. The quoted sentences say what the papers report.
lung carcinoma (4 papers, 2015 to 2021). "It has been reported that SRSF1 was able to regulate EMT through disrupting the alternative splicing of key tumor associated genes, including Ron proto-oncogene, PRRC2C, and MKNK2, to modulate lung cancer progression." (PMID 31832019, 2019). "More recently, SRSF1 overexpression was also reported in lung cancer and novel SRSF1 target transcripts were identified, including the genes, ATP11C, IQCB1, TUBD1, proline-rich coiled-coil 2C (PRRC2C), and survivin." (PMID 26273603, 2015).
bladder cancers (1 paper, 2012). "It has also been reported that the PRRC2C gene is amplified and overexpressed in approximately 30% of bladder cancers, although our subsequent validation experiments eliminated this gene as a common amplified and overexpressed cancer gene." (PMID 22912832, 2012).
cognitive decline (1 paper, 2016). "Interestingly, the PRRC2C gene associated has been associated with cognitive decline in AD." (PMID 27656889, 2016).
lower respiratory tract infections (1 paper, 2022). "A previous study demonstrated that host transcriptome profiles helped build a host transcriptional classifier (NFAT-5, ZC3H11A, and PRRC2C) for diagnosing lower respiratory tract infections with an AUC of 0.88 (95% CI, 0.75-1.00)." (PMID 36483456, 2022).
cancer (3 papers, 2012 to 2023). A tumor composed of atypical neoplastic, often pleomorphic cells that invade other tissues. "Nevertheless, other four cancer-related candidate proteins (KI67, NUMA1, EIF5B and PRRC2C) could not be validated in cells." (PMID 37072811, 2023).
PRRC2C also shares sentences with these, for which no sentence is quoted: tumor (3 papers); cerebellar ataxia (1); Hypertension (1); Intellectual disability (1); Obesity (1).